MAP2K1P2 (MAP2K1 pseudogene 2)
Synonyms: formerly MAP2K2L
Gene: Transcribed processed pseudogene on chromosome 7 (129,126,518 to 129,127,715, forward strand). Ensembl gene ENSG00000230626.
Genetic constraint (gnomAD): Loss-of-function variants: 13 observed, 12.5 expected, observed/expected ratio (o/e) 1.04, 90% interval 0.68 to 1.63. Missense variants: 303 observed, 306.65 expected, observed/expected ratio (o/e) 0.99, 90% interval 0.9 to 1.09. Synonymous variants: 131 observed, 128.99 expected, observed/expected ratio (o/e) 1.02, 90% interval 0.88 to 1.17.